PDGFC (platelet derived growth factor C)
Description:
Growth factor that plays an essential role in the regulation of embryonic development, cell proliferation, cell migration, survival and chemotaxis. Potent mitogen and chemoattractant for cells of mesenchymal origin. Required for normal skeleton formation during embryonic development, especially for normal development of the craniofacial skeleton and for normal development of the palate. Required for normal skin morphogenesis during embryonic development. Plays an important role in wound healing, where it appears to be involved in three stages: inflammation, proliferation and remodeling. Plays an important role in angiogenesis and blood vessel development. Involved in fibrotic processes, in which transformation of interstitial fibroblasts into myofibroblasts plus collagen deposition occurs. The CUB domain has mitogenic activity in coronary artery smooth muscle cells, suggesting a role beyond the maintenance of the latency of the PDGF domain. In the nucleus, PDGFC seems to have additional function.
Synonyms: SCDGF; fallotein
Tractability: Antibody: UniProt places it where antibodies can reach, with high confidence; its Gene Ontology location is reachable by antibodies, with high confidence; UniProt predicts a signal peptide or a membrane-spanning region; the Human Protein Atlas places it where antibodies can reach. PROTAC: UniProt records ubiquitination sites on it.
Gene: Protein-coding gene on chromosome 4 (156,760,454 to 156,971,799, reverse strand). Ensembl gene ENSG00000145431.
Subcellular location: Cytoplasm, cytosol; Secreted; Nucleus; Cytoplasmic granule; Cell membrane
Subcellular location (Human Protein Atlas): Cytosol; Plasma membrane; Predicted to be secreted
Pathways (Reactome):
Signal Transduction: Signaling by PDGF
Gene Ontology:
Molecular function: platelet-derived growth factor receptor binding; protein binding; protein homodimerization activity; growth factor activity
Biological process: platelet-derived growth factor receptor signaling pathway; positive regulation of cell population proliferation; positive regulation of fibroblast proliferation; central nervous system development; positive regulation of cell migration; positive regulation of cold-induced thermogenesis; positive regulation of ERK1 and ERK2 cascade; positive regulation of phosphatidylinositol 3-kinase/protein kinase B signal transduction
Cellular component: cell surface; cytosol; extracellular exosome; extracellular region; nucleus; plasma membrane; endoplasmic reticulum lumen; Golgi membrane; membrane
Genetic constraint (gnomAD): Loss-of-function variants: 0 observed, 8.84 expected, observed/expected ratio (o/e) 0, 90% interval 0 to 0.34. That is too few expected variants to judge how well the gene tolerates losing a copy. Missense variants: 111 observed, 155.14 expected, observed/expected ratio (o/e) 0.72, 90% interval 0.61 to 0.84. Synonymous variants: 56 observed, 58.41 expected, observed/expected ratio (o/e) 0.96, 90% interval 0.77 to 1.2.
Homologues: Orthologues: chimpanzee PDGFC (99% identical), rabbit PDGFC (96% identical), dog PDGFC (95% identical), pig PDGFC (94% identical), macaque PDGFC (90% identical), mouse Pdgfc (87% identical), rat Pdgfc (79% identical), tropical clawed frog pdgfc (70% identical), guinea pig PDGFC (65% identical), zebrafish pdgfc (62% identical). Paralogues in human: PDGFD (44% identical), CNTNAP3 (22% identical), CNTNAP3B (22% identical), CNTNAP5 (21% identical), CNTNAP4 (20% identical), CNTNAP2 (19% identical), NRP1 (18% identical), NRP2 (18% identical), HEPH (18% identical), HEPHL1 (18% identical), CUBN (17% identical), CP (17% identical), and 23 more.
Diseases named in the same sentence as PDGFC in open-access papers:
PDGFC is named in the same sentence as 101 diseases in open-access papers, as found by Europe PMC text mining. Sharing a sentence is not in itself a finding about the gene and the disease. The quoted sentences say what the papers report.
breast cancer (15 papers, 2014 to 2025). A primary or metastatic malignant neoplasm involving the breast. "Besides, upregulated PDGFC expression is associated with the histological grade and stage of breast cancer patients, and its knockdown has decreased invasion and proliferation in breast cancer cells." (PMID 38167429, 2024). "Interestingly, PDGFC is also associated with features of inferior prognosis in human breast cancer and the PDGFC gene strongly correlates with gene-sets defining the EMT pathways supporting an association also for PDGFC with EMT." (PMID 32300922, 2020). "Platelet-derived growth factor-C (PDGF-C) is overexpressed in various malignancies; however, the involvement of PDGF-C in breast cancers and the mechanisms underlying PDGF-C deregulation remain unclear." (PMID 25383675, 2014). "In the breast cancer lung metastasis model, the platelet-derived growth factor C (PDGF-C) level in the microenvironment increases when lung tissue becomes senescent or fibrotic." (PMID 39966355, 2025). "The situation is less clear in human tumors, with the Molecular Taxonomy of Breast Cancer International Consortium (METABRIC) dataset revealing higher PDGFC expression in ER+ breast cancers than in ER− breast cancers." (PMID 36914817, 2023). "In malignant breast tumors, PDGFC mediates antiapoptotic effects through Akt/Bad phosphorylation, underlining the important role of PDGFC in cell growth and survival through resident macrophages in tumors." (PMID 35422475, 2022). "In line with the overexpression results, knocking down Roquin2 increased the mRNA levels of angiogenic genes, including ENG, EDN1, VEGFB, and PDGFC in breast cancer cells." (PMID 34345214, 2021). "High PDGFD protein levels also positively correlated with a higher T stage and positive lymph node status in colorectal cancer while a high PDGFC protein level has been shown to correlate with positive lymph node status in breast cancer." (PMID 33918816, 2021). "Serum levels of vascular endothelial growth factor (VEGF), metalloproteinase-11 (MMP-11), and platelet-derived growth factor-C (PDGF-C) were also greater in breast cancer patients compared to healthy volunteers." (PMID 26456994, 2015). "Comparing PDGFC expression across a broader range of breast cancer molecular subtypes, as well as evaluating the activity of the PDGFC/NRG1 signaling axis between tumor cells and fibroblasts, will provide valuable insights for the development of more precise therapeutic strategies in breast cancer." (PMID 41213930, 2025). "Indeed, expression of PDGFC was inversely correlated with ESR1 expression in breast cancer cell lines, and Pdgfc expression was significantly lower in cultured ER+ TSAE1 and HRM1 tumor cells than in ER− D2A1 and 4T1 cells." (PMID 36914817, 2023). "We also explored the downstream signaling pathways of the PDGFC and PDGFRA complex in TRZ resistant breast cancer cells." (PMID 36979654, 2023). "Meanwhile, we observed differential expression of PDGFC between different cell lines, such as MCF-7 and MDA-MB-231, which may be attributed to the distinct breast cancer subtypes or other tumor cell heterogeneity." (PMID 41213930, 2025). "In Roquin2-overexpressing MDA-MB-468 and MCF7 cells, we found that proangiogenic factors mRNA, including PDGFC, ENG, EDN1, and VEGFB, were downregulated in two breast cancer cells, while the mRNA expression of antiangiogenic genes, including TIMP1/3, SERPINF1, and ANGPTL4 were upregulated." (PMID 34345214, 2021). "EDN1 and PDGFC stem-loop sequences could be amplified in the groups pulled down with anti-GFP antibody but not the isotype IgG, suggesting that Roquin2 binds to the stem-loop in the 3'UTRs of angiogenic mRNAs inside breast cancer cells." (PMID 34345214, 2021).
breast cancer (continued). "A novel finding in the present study is that the partial and mesenchymal EMT phenotypes displayed a high fraction of EGFR and PDGFC positivity compared with the epithelial and negative phenotypes, further supporting that these phenotypes define an aggressive type of breast cancer." (PMID 32300922, 2020).
liver fibrosis (12 papers, 2011 to 2023). "The anti-fibrotic effect of BCAA was confirmed further using platelet-derived growth factor C transgenic mice, which develop hepatic fibrosis and tumors." (PMID 28212548, 2017).
melanoma (12 papers, 2009 to 2025). A malignant, usually aggressive tumor composed of atypical, neoplastic melanocytes. "Among the up-regulated oncogenes in melanoma, ABL2, NRAS, PDGFC and FGF1 have been reported to be melanoma-associated oncogenes." (PMID 22295108, 2012). "It was previously reported that PDGFC activated EMT processes and increased melanoma aggressiveness by regulating SLUG expression." (PMID 33603171, 2021). "In melanomas, genes coordinately expressed with GPC6 were largely those involved in cell adhesion and migration including INHBA, PDGFC, PDGFRA, PPAP2B, SPRX2, TCF4, and TNFAIP6 and ZEB1." (PMID 31199813, 2019). "In addition, five genes (FGF10, FGF2, MITF, PDGFC, and PDGFD) were involved in “Melanoma”, which might be associated with the two-end black pigmentation observed in BMX pigs, which differs from most Chinese domestic pigs with black coats (China National Commission of Animal Genetic Resources, 2011)." (PMID 29955027, 2018). "However, the genes ANXA1, PDGFC, VEGFC and LRRN3 were downregulated in CL1-0 shMITF-harboring cells, while they were upregulated in si-MITF melanoma 501MEL cells." (PMID 33293474, 2020). "Since melanoma cells co-expressing high levels of NRP-1 and platelet derived growth factor-C (PDGF-C) show a highly invasive behaviour and PDGF-C shares homology with VEGF-A, in this study we have investigated whether PDGF-C directly interacts with NRP-1 and promotes melanoma aggressiveness." (PMID 28977999, 2017).
fibrosis (6 papers, 2013 to 2024). the formation of excess fibrous connective tissue in an organ or tissue in a reparative or reactive process. "Upregulated expression of platelet-derived growth factor C (PDGFC) expression in the aged microenvironment and bleomycin-induced fibrosis can promote metastasis, showing the importance of the microenvironment in DTC activation." (PMID 37801168, 2023). "The co-localization of PDGFC- PDGFRA interaction with fibrotic areas and markers was notably more pronounced in slides obtained from MASH patients with fibrosis stage 3 and 4 scores, compared to healthy samples or those with fibrosis stage 1 and 2 scores." (PMID 38768139, 2024).
glioma (6 papers, 2009 to 2021). A benign or malignant brain and spinal cord tumor that arises from glial cells (astrocytes, oligodendrocytes, ependymal cells). "Other downregulated genes include an interferon-γ receptor IFNGR2, integrin subunits ITGA/B, and PDGFC, which can de-differentiate astrocytes in glioma cell lines." (PMID 31231645, 2019). "Furthermore, studies on the PDGFC and D ligands, also demonstrate their expression in gliomas; however, the clinical and biological significance of their expression remain to be determined." (PMID 19707201, 2009).
hepatocellular carcinoma (6 papers, 2014 to 2024). A malignant tumor that arises from hepatocytes. "Remarkably, the association of PDGFC expression has been linked not only to the progression of fibrosis, but also to chronic inflammation, increment of collagen production, hepatocarcinogenesis, steatosis, hepatocellular carcinoma." (PMID 38768139, 2024). "After treatment with sorafenib, hepatoma cells upregulate miRNA-375 expression and downregulate the expression of platelet-derived growth factor C (PDGFC), inhibit the phosphorylation of its downstream signaling pathways ERK1/2, AKT, and play a role in inhibiting angiogenesis." (PMID 37427386, 2023).
pancreatic cancer (6 papers, 2004 to 2025). "The FTO-mediated upregulation of platelet-derived growth factor C (PDGFC) autocrine signaling through the m6A/YTHDF2 axis drives pancreatic cancer progression." (PMID 40986143, 2025). "Recent research has shown that FTO has an oncogenic impact on pancreatic cancer by directly targeting PDGFC (platelet-derived growth factor C) and stabilizing mRNA expression through m6A." (PMID 37605223, 2023). "Another example of the oncogenic role of FTO was observed in pancreatic cancer, where FTO induced cancer progression via stabilizing the mRNA of platelet-derived growth factor C (PDGFC)." (PMID 38503745, 2024). "In pancreatic cancer cells, inhibiting FTO expression reduces cell proliferation by increasing the m6A modification of the 3′ UTR region of platelet-derived growth factor-C (PDGFC) and regulates the degradation of PDGFC at the transcriptional level in an m6A-YTHDF2 dependent manner." (PMID 36358640, 2022).
diabetes (5 papers, 2015 to 2022). "Furthermore, tadalafil enhanced diabetes-reduced nerve growth factor (NGF) and platelet-derived growth factor-C (PDGF-C) protein levels in diabetic sciatic nerve tissue." (PMID 27438594, 2016).
lung fibrosis (5 papers, 2014 to 2026). "In summary, our findings highlight lactate metabolism, particularly via SLC16A4 and PDGFC–PDGFRA signaling, as a potential driver of COVID‐19–associated pulmonary fibrosis and a promising target for future therapeutic intervention." (PMID 41532065, 2026).
atherosclerosis (4 papers, 2019 to 2024). A disease characterized by the build-up of fatty material and calcium deposition in the arterial wall resulting in partial or complete occlusion of the arterial lumen. "PDGFC, a member of platelet-derived growth factor (PDGF), has been reported to be associated with chronic rejection of cardiac transplantation, upregulating TGF-β1 and promoting myocardial fibrosis and atherosclerosis." (PMID 37753085, 2023).
colorectal cancer (4 papers, 2018 to 2024). A primary or metastatic malignant neoplasm that affects the colon or rectum. "For instance, we showed that, in colorectal cancer, PrPC controls the expression of Platelet-Derived Growth Factor C (PDGFC), a stimulator of angiogenesis." (PMID 34638517, 2021). "Thus, the study of multiple regions of CMS4 colorectal cancers and the analysis of PDGFRA, PDGFRB, PDGFC and KIT showed the existence of a consistent intratumor heterogeneity." (PMID 29652830, 2018).
glioblastoma (4 papers, 2009 to 2024). The most malignant astrocytic tumor (WHO grade IV). "We analysed gene expression of the PDGF system (PDGFA, PDGFB, PDGFC, PDGFD, PDGFRA, PDGFRB) in 36 GBMs studied on Ivy Glioblastoma Atlas Project." (PMID 29127351, 2017).
brain tumor (3 papers, 2009 to 2023). "It is known that PDGFC can trigger the initiation and progression of brain tumors." (PMID 36979654, 2023).
Insulin resistance (3 papers, 2016 to 2022). Increased resistance towards insulin, that is, diminished effectiveness of insulin in reducing blood glucose levels. "Furthermore, while experiments in the model systems will be required to validate many of the most promising targets, some genes such as FAM13A and PDGFC have already been partially validated within the context of insulin resistance." (PMID 35292083, 2022).
lymphoma (3 papers, 2015 to 2022). A malignant (clonal) proliferation of B- lymphocytes or T- lymphocytes which involves the lymph nodes, bone marrow and/or extranodal sites. "For instance, in lymphoma platelet-derived growth factor C (PDGF-C) secreted by CAFs can counteract the antiangiogenesis therapy by anti-VEGF antibodies, as PDGF-C substitutes VEGF in stimulating capillary outgrowth thus diminishing the treatment efficacy." (PMID 25588753, 2015). "One study revealed that CAFs extracted from anti-VEGF resistance murine lymphoma cell line (EL4) could effectively resist the anti-VEGF therapy in otherwise sensitive murine myeloma cell line (TIB6) via platelet-derived growth factor-C (PDGF-C) mediation." (PMID 30680600, 2019). "Finally, CAFs mediated resistance to VEGF inhibitors in lymphoma xenografts models, by reactivating angiogenesis through platelet-derived growth factor C (PDGF-C) signaling, and PDGF-C targeting showed additive effects with anti-VEGFA antibodies." (PMID 36324182, 2022).
bladder cancer (2 papers, 2021). "In the current study we correlated NRP, PDGFC and PDGFD messenger expression with clinical outcomes in bladder cancer." (PMID 33918816, 2021).
breast tumor (2 papers, 2021 to 2025). "In addition, PDGFC is expressed in CAFs, and CAF-derived PDGFC has been shown to be related to growth, metastasis, epithelial-mesenchymal transition (EMT) and drug resistance in gastrointestinal and basal-like breast tumors." (PMID 40501228, 2025).
cardiomyopathy (2 papers, 2016 to 2023). A disease of the heart muscle or myocardium proper. "Microvascular network growth and the angiogenic properties of the TAT in elderly patients with cardiomyopathy also seem to involve the upregulation of PDGFC, FGF2, NOTCH2, FOS, JAG1, and PDGFRA target genes." (PMID 37833902, 2023).
cleft palate (2 papers, 2009 to 2016). Cleft palate is a fissure type embryopathy that affects the soft and hard palate to varying degrees. "Reduced PDGFC by retinoic acid may cause inhibition of proliferation in palatal shelves, resulting in the pathogenesis of cleft palate in Pdgfc−/− mice or retinoic acid-treated mice." (PMID 19401770, 2009).
COVID-19 (2 papers, 2022 to 2023). A disease caused by infection with severe acute respiratory syndrome coronavirus 2. "Additionally, the expression of genes associated with endothelial dysfunction—namely CCL2, PDGFRA, PDGFB, and PDGFC—was also found to be increased in ACE2-positive brain cells of COVID-19 patients." (PMID 37239234, 2023). "Further, the expression of genes involved in endothelial dysfunction, namely CCL2, PDGFRA, PDGFB, and PDGFC, is found to be increased in ACE2-positive brain cells of COVID-19 patients." (PMID 37239234, 2023). "In addition, platelet-derived growth factor C (PDGFC) and receptor alpha (PDGFRA) were found to be more abundant in the COVID-19 group, with PDGFRA displaying such a trend only in the survivor subgroup." (PMID 35842415, 2022).
lung adenocarcinoma (2 papers, 2020 to 2025). A carcinoma that arises from the lung and is characterized by the presence of malignant glandular epithelial cells. "Moreover, the expression of VEGFC and PDGFC was associated with longer survival time of lung adenocarcinoma patients." (PMID 33293474, 2020). "This study elucidates the mechanisms by which cancer-associated fibroblast (CAF)-derived platelet-derived growth factor C (PDGFC) promotes the progression of lung adenocarcinoma (LUAD) and explores the impact of PDGFC on immune regulation within the tumor microenvironment (TME)." (PMID 40501228, 2025). "Furthermore, the expression levels of ANXA1, VEGFC, PDGFC and LRRN3 were significantly positively associated with the survival of lung adenocarcinoma." (PMID 33293474, 2020).
metastatic disease (2 papers, 2017 to 2022). "Since the expression levels of CTHRC1, FBN2, NTM, PDGFC, PDLIM3, and SLC16A3 are significantly differentiated among the normal samples, primary tumor, and metastatic tumor, we anticipated that these genes are associated with metastasis in colon cancer." (PMID 35991839, 2022). "Interestingly, we found that CTHRC1, NTM, PDGFC, PDLIM3, and SLC16A3 are gradually upregulated from normal to a metastatic tumor, indicating the association of these genes in tumor progression (Welch’s t-test, p < 0.05)." (PMID 35991839, 2022). "PDGFC is correlated with early diagnosis, cancer grading, and metastatic disease of CRC." (PMID 35991839, 2022). "Moreover, the CTHRC1, PDGFC, PDLIM3, NTM, and SLC16A3 genes are gradually increased from normal tissue to the tumor and tumor to the metastatic tumor, and FBN2 showed the reverse pattern." (PMID 35991839, 2022).